OLAH (oleoyl-ACP hydrolase)
Description:
Contributes to the release of free fatty acids from fatty acid synthase (FASN). Has broad substrate specificity, giving rise to a range of free fatty acids with chain lengths between 10 and 16 carbon atoms (C10 - C16).
Synonyms: AURA1; TE2; THEDC1; SAST; FLJ11106
Tractability: No criterion of Open Targets' tractability assessment is met for any kind of drug.
Gene: Protein-coding gene on chromosome 10 (15,032,227 to 15,073,853, forward strand). Ensembl gene ENSG00000152463.
Subcellular location: Cytoplasm, cytosol
Pathways (Reactome):
Metabolism: Fatty acyl-CoA biosynthesis
Gene Ontology:
Molecular function: fatty acyl-[ACP] hydrolase activity; long-chain fatty acyl-CoA hydrolase activity; medium-chain fatty acyl-CoA hydrolase activity
Biological process: medium-chain fatty acid biosynthetic process; lipid biosynthetic process
Cellular component: cytosol
Genetic constraint (gnomAD): Loss-of-function variants: 19 observed, 17.84 expected, observed/expected ratio (o/e) 1.06, 90% interval 0.74 to 1.56. The upper end of that interval is the gene's LOEUF score, 1.56, which puts it in group 6 of 6, group 1 being the genes least tolerant of losing a copy. Missense variants: 206 observed, 191.2 expected, observed/expected ratio (o/e) 1.08, 90% interval 0.96 to 1.21. Synonymous variants: 64 observed, 60.92 expected, observed/expected ratio (o/e) 1.05, 90% interval 0.86 to 1.29.
Homologues: Orthologues: chimpanzee OLAH (95% identical), macaque OLAH (87% identical), guinea pig OLAH (62% identical), mouse Olah (59% identical), rat Olah (56% identical), tropical clawed frog olah (45% identical), zebrafish olah (39% identical).
Diseases named in the same sentence as OLAH in open-access papers:
OLAH is named in the same sentence as 19 diseases in open-access papers, as found by Europe PMC text mining. Sharing a sentence is not in itself a finding about the gene and the disease. The quoted sentences say what the papers report.
Sepsis (7 papers, 2021 to 2025). Sepsis is defined as life-threatening organ dysfunction caused by a dysregulated host response to infection. "OLAH (oleoyl-ACP hydrolase) is involved in fatty acid metabolism, and altered lipid handling has been linked to immune suppression in late-stage sepsis." (PMID 41333476, 2025). "ELANE, MPO, CD177, OLFM4 and OLAH gene expression were found to be comparable in both the groups sepsis and sterile inflammation indicating that neutrophil response to both bacterial infection and tissue injury involved upregulation of these genes." (PMID 34552111, 2021). "The results showed significantly higher levels of OLAH, HPGD, and LY96 in sepsis patients compared to those with preoperative conditions or pneumonia, increased by 95.16-, 6.58-, and 2.89-fold, respectively, while ABLIM1 was downregulated by 7.33-fold." (PMID 39628572, 2024). "The refined model, comprising genes OLAH, LY96, HPGD, and ABLIM1, demonstrated high predictive accuracy for 28-day mortality and excelled in early sepsis detection." (PMID 39628572, 2024). "Nineteen high-performance, differentially expressed mRNA biomarkers were identified between control and combined SIRS/Sepsis groups (FC>20.0, p<0.05), termed ‘indicators of inflammation’ (I°I), including CD177, FAM20A and OLAH." (PMID 38332914, 2023). "Classification of data split into three separate groups: Controls, SIRS and Sepsis achieved an OOB estimate of error rate of 17.99% across all days, revealing three biomarkers of most importance by feature selection i.e., FAM20A, OLAH and DAAM2." (PMID 38332914, 2023). "DAAM2 and OLAH were significantly upregulated in both SIRS (FC>8) and sepsis (FC>20) compared to controls, but approximately 3-fold higher in sepsis, than SIRS." (PMID 38332914, 2023). "Gene entities exhibiting stronger expression in the SIRS-ranked dataset included CFC1, CT62, lnc-DAAM2-1 and lnc-LTBP3-2 and in the sepsis-ranked dataset included TDRD9, DAAM2, OLFM4 and OLAH." (PMID 38332914, 2023). "Providing external validation to our findings, several genes, such as CD177, ARG1 (arginase), MMP9, OLAH and ADM have been described previously as having important inflammatory roles in sepsis." (PMID 38332914, 2023). "A cut-off value of -14.0 was selected for panel ADM+FAM20A+ITGA7+MPP9+OLAH for discrimination of SIRS and sepsis groups from controls, which provides a positive predictive value (PPV) and negative predictive value (NPV) each of 100%." (PMID 38332914, 2023). "Artificial intelligence systems identified eight out of twenty novel genetic markers (SDC4, CLEC5A, TCN1, MS4A3, HCAR3, OLAH, PLCB1, and NLRP1) that help predict sepsis severity or mortality." (PMID 33692779, 2021). "Differentially expressed genes between 28-day survivors and non-survivors include transcripts previously linked to sepsis outcomes such as IL1R2, OLAH, and CX3CR1 6,41." (PMID 38890515, 2024). "Logistic regression was used to assess the likelihood of sepsis based on CA4, OLAH, and VNN1." (PMID 37608823, 2023). "In contrast, OLAH and VNN1 showed low expression across all major immune cell types, suggesting that these genes may be expressed in non-immune blood components (e.g., endothelial cells or platelets) and contribute to sepsis progression through indirect mechanisms." (PMID 41333476, 2025).
COVID-19 (4 papers, 2023 to 2025). A disease caused by infection with severe acute respiratory syndrome coronavirus 2. "A recent publication linked high expression of oleoyl-ACP hydrolase (Olah) to life-threatening respiratory illnesses, particularly COVID-19." (PMID 40163145, 2025). "Given that OLAH expression was conspicuously amplified in fatal COVID-19 both in the upper respiratory tract and blood, and because OLAH was recently implicated in the pathogenesis of severe viral pneumonia, we also evaluated its performance in a single-gene classifier." (PMID 41212055, 2025). "Here, we independently validated the association of both airway and peripheral blood OLAH expression with COVID-19 severity, and we provide what we believe to be the first assessment of its performance as a prognostic biomarker in 2 large cohorts of hospitalized patients." (PMID 41212055, 2025). "High OLAH levels have been reported in patients with life-threatening viral disease, including COVID-19, suggesting a role a role viral pathogenesis." (PMID 40163145, 2025). "OLAH, a metabolic enzyme in medium-chain fatty acid biosynthesis, has been correlated with T cell signaling and poor prognosis in COVID-19 immunopathology, underscoring its potential as a critical factor in T cell activation." (PMID 39628572, 2024). "In severely ill COVID-19 patients, elevated levels of OLAH were observed." (PMID 40163145, 2025). "In a large, prospective, multicenter cohort, we find that either a single gene, OLAH, or a combination of 3 genes, CD83, ATP1B2, and DAAM2, accurately predicted 28-day mortality in hospitalized patients with COVID-19, including those who have been vaccinated." (PMID 41212055, 2025).
viral disease (3 papers, 2025). "The authors previously pinpointed OLAH (oleoyl-ACP-hydrolase) as a driver of life-threatening viral diseases." (PMID 41285788, 2025). "Our recent findings identified OLAH (oleoyl-ACP-hydrolase) as a driver of life-threatening viral diseases." (PMID 41285788, 2025). "Notably, OLAH, the most strongly upregulated gene in both PBMC and nasal swab and recently implicated in severe viral infection pathogenesis, yielded AUCs of 0.86 (0.79–0.93) and 0.78 (95% CI, 0.69–0.86), respectively." (PMID 41212055, 2025).
preeclampsia (2 papers, 2021 to 2022). Preeclampsia is a hypertensive disorder of pregnancy that is characterized by new-onset hypertension with proteinuria presenting after 20 weeks of gestation, and depending on mild or severe forms may initially present with severe headache, visual disturbances, and hyperreflexia. "As placental dysfunction is central to the pathogenesis of both fetal growth restriction and preeclampsia, we aimed to investigate OLAH levels and function in the human placenta." (PMID 36139751, 2022). "In contrast, OLAH levels were high in placenta collected from pregnancies complicated by preterm preeclampsia." (PMID 36139751, 2022). "In previous studies, our group demonstrated that OLAH transcripts were highly upregulated in the maternal circulation of individuals whose pregnancies were complicated by fetal growth restriction and preeclampsia." (PMID 36139751, 2022). "We therefore went on to investigate a potential role for OLAH in placental cytotrophoblasts in the pathogenesis of fetal growth restriction and preeclampsia." (PMID 36139751, 2022). "Noting that OLAH transcripts are highly increased in the circulation of cases of preeclampsia and growth restriction, we next examined OLAH levels in the pathological placenta, as placental dysfunction is central to the pathophysiology of both conditions." (PMID 36139751, 2022). "Nevertheless, we did interestingly find that OLAH protein in growth-restricted placental tissue was significantly lower than that in the placental samples collected from cases of preeclampsia." (PMID 36139751, 2022). "We assessed OLAH expression and protein in placental tissue from individuals with preterm preeclampsia and fetal growth restriction, compared to preterm control placental tissue." (PMID 36139751, 2022). "OLAH mRNA and protein levels (Western blot) were elevated in placental tissue from cases of preterm preeclampsia, while OLAH protein levels in placenta from growth-restricted pregnancies were comparatively reduced in the preeclamptic cohort." (PMID 36139751, 2022). "Using next-generation sequencing, we previously identified that OLAH transcripts are elevated in the maternal circulation in pregnancies complicated by fetal growth restriction, approximately half of which had preeclampsia." (PMID 36139751, 2022). "In this study, we found that placental hypoxia significantly increased OLAH mRNA expression in placental explant tissue, similar to our findings in placental tissue from cases of preeclampsia, suggesting that impaired oxygen delivery may cause OLAH dysregulation in preeclampsia." (PMID 36139751, 2022). "This suggests that OLAH may have a unique function in the human placenta and could potentially be involved in the pathogenesis of preeclampsia, a human-specific condition." (PMID 36139751, 2022). "Here, we assessed whether OLAH regulates the expression and release of these factors from isolated cytotrophoblast, which would implicate OLAH in the regulation of angiogenesis in preeclampsia." (PMID 36139751, 2022). "Assessing pathways altered with OLAH overexpression may give further insight into the implications of OLAH dysregulation in the placenta, especially because placental OLAH is elevated in preeclampsia and with placental hypoxia." (PMID 36139751, 2022). "Similarly, another study found that cytotrophoblast cells isolated from placentas experiencing preeclampsia had significantly elevated OLAH mRNA, compared to preterm labor controls." (PMID 36139751, 2022). "Here, using data from the same sample set, we sought to evaluate whether those pregnancies that were also complicated by preeclampsia had further altered levels of circulating OLAH transcripts, compared to pregnancies complicated by fetal growth restriction alone (normotensive)." (PMID 36139751, 2022).
preeclampsia (continued). "However, we note that while OLAH protein levels in each of the samples from the preeclampsia and growth restriction groups were clustered together, the OLAH protein levels in the preterm controls were quite variable, and thus could have confounded our results." (PMID 36139751, 2022). "We next investigated OLAH in the placenta, as increased OLAH levels in the pathological placenta could contribute to the elevated levels of circulating OLAH transcripts, especially as both fetal growth restriction and preeclampsia can feature a dysfunctional placenta." (PMID 36139751, 2022). "Dysregulation of OLAH protein in these two diseases may contribute to differences previously identified in the fatty acid profile of maternal and umbilical cord plasma in pregnancies affected by fetal growth restriction alone versus preeclampsia with fetal growth restriction." (PMID 36139751, 2022). "Thus, in preeclampsia, elevated placental OLAH could be beneficial." (PMID 36139751, 2022). "We found that OLAH mRNA transcripts were not further significantly altered in the maternal circulation when pregnancies were also complicated by preeclampsia (plus growth restriction) compared to normotensive pregnancies with fetal growth restriction." (PMID 36139751, 2022). "Intriguingly, we found that placentas collected from cases of preeclampsia, but not fetal growth restriction, had significantly elevated OLAH mRNA expression compared to preterm controls." (PMID 36139751, 2022). "Although OLAH mRNA expression was elevated with preeclampsia, OLAH protein was not significantly different compared to control." (PMID 36139751, 2022). "Under hypoxia (mimicking conditions of placental dysfunction akin to that in preeclampsia), silencing cytotrophoblast OLAH did not alter the expression of the two sFLT1 transcript isoforms, sFLT-e15a or sFLT-i13, nor secretion of the functional sFLT1 protein." (PMID 36139751, 2022). "In this study, we identified that OLAH is expressed in the placenta throughout gestation, and importantly, its levels are altered in the placenta in cases of fetal growth restriction and preeclampsia (without fetal growth restriction), and under hypoxic conditions." (PMID 36139751, 2022). "Placental mRNA expression of OLAH was significantly increased in preterm preeclampsia (without fetal growth restriction) (p = 0.0004) compared to preterm control, but was not altered in fetal growth restriction alone, or preeclampsia with fetal growth restriction." (PMID 36139751, 2022). "Hence, we cannot make a statement on what increased placental OLAH could mean in preeclampsia without further studies, except to suggest that this elevated OLAH may mean increased lipid processing into medium-chain fatty acids, which may move more readily to the fetus for fetal growth." (PMID 36139751, 2022).
Arthritis (1 paper, 2025). Inflammation of a joint. "OLAH was connected to ADAMTS2 in both responders and nonresponder networks; the ADAMTS family are involved in extracellular matrix remodeling and linked to arthritis." (PMID 40415615, 2025).
fetal growth restriction (1 paper, 2022). A fetus that does not grow beyond the 10th percentile of conventionally accepted weight for gestational age. "Previously, we identified elevated transcripts for the gene Oleoyl-ACP Hydrolase (OLAH) in the maternal circulation of pregnancies complicated by preterm fetal growth restriction." (PMID 36139751, 2022). "As we have detected low OLAH protein in placentas from cases of fetal growth restriction, we suggest that OLAH could play an important role in disease pathogenesis and could be an important target for improving fetal growth." (PMID 36139751, 2022). "As OLAH protein is low in fetal growth restriction, it is possible that its reduction in disease could decrease IGF2 as well." (PMID 36139751, 2022). "In a sub-analysis of the OLAH transcripts measured in the maternal circulation of pregnancies complicated by fetal growth restriction, we found no further changes when we split the cases by hypertensive status or fetal hypoxia." (PMID 36139751, 2022).
influenza infection (1 paper, 2025). "OLAH-KO mice demonstrated protection against severe influenza infection, reduced inflammatory damage, and improved control of viral replication, outcomes attributed to modulating lipid mediators of inflammation." (PMID 41212055, 2025).
cardiac disease (1 paper, 2022). "In fact, medium chain fatty acids, which are the products of OLAH-catalyzed reactions, are being considered for their therapeutic benefits on metabolic health in cardiac disease." (PMID 36139751, 2022).
infection (1 paper, 2025). The state of being infected such as from the introduction of a foreign agent such as serum, vaccine, antigenic substance or organism. "Our previous whole blood transcriptome analysis in patients hospitalized with severe A(H7N9) infection in China in 2013 identified OLAH as the early driver of fatal disease outcomes." (PMID 41285788, 2025).
OLAH also shares sentences with these, for which no sentence is quoted: bacterial infection (2 papers); breast carcinoma (2); rheumatoid arthritis (2); cancer (1); neuroblastoma (1); non-small cell lung carcinoma (1); Obesity (1); oligospermia (1); pneumonia (1); viral pneumonia (1).